JAK2 (Janus kinase 2)
Diseases named in the same sentence as JAK2 in open-access papers (continued):
Sharing a sentence is not in itself a finding about the gene and the disease.
atherosclerosis (65 papers, 2014 to 2026). A disease characterized by the build-up of fatty material and calcium deposition in the arterial wall resulting in partial or complete occlusion of the arterial lumen. "Even in the presence of lower cholesterol levels, mice with JAK2 mutations developed accelerated atherosclerosis, suggesting that these mutations act as potent drivers of CVD." (PMID 39997650, 2025). "Clonal hematopoiesis (CH), driven by mutations in genes such as JAK2, has been implicated in the pathogenesis of atherosclerosis, particularly by modulating macrophage function and autophagy." (PMID 40244103, 2025). "JAK2 mutations in HSCs can lead to CH and correlate with atherosclerosis, but the condition has been difficult to study because of challenges modeling the mutant cells at very low frequency." (PMID 39744945, 2025). "In conclusion, platelet Jak2 deficiency caused accelerated atherosclerosis through increased inflammatory response of platelets, macrophages, and HSPCs." (PMID 40825505, 2025). "Experimental atherosclerosis was increased in females with Tet2 and males with Jak2, but it was unchanged with Dnmt3a mutations." (PMID 41433101, 2025). "Recently, accumulating evidence has indicated that JAK2 phosphorylation is linked to cardiovascular conditions, including atherosclerosis, diabetes mellitus, myocardial fibrosis, and myocardial ischemia–reperfusion injury." (PMID 40647133, 2025). "JAK2 V617F mutation promotes pro-inflammatory cytokine release, exacerbates endothelial damage and leukocyte infiltration, and increases the risk of atherosclerosis, requiring statin lipid-lowering therapy." (PMID 40926892, 2025). "Chronic inflammation underlies atherosclerosis, and Janus kinase 2 (Jak2) is a critical signaling node that mediates this process." (PMID 40825505, 2025). "Pro-inflammatory pathways, including IL-1β/IL-6 signaling, NLRP3 inflammasome activation, and JAK2-mediated thrombo-inflammation, explain its role in atherosclerosis, metabolic dysfunction, and thrombotic risk, highlighting druggable targets for prevention." (PMID 41516113, 2025). "To this end, we assessed the in vivo role of platelet Jak2 in atherosclerosis using ApoE−/− mice with platelet Jak2 deficiency." (PMID 40825505, 2025). "Despite Jak2 being a known mediator of inflammatory signaling, our work shows that deficiency of platelet Jak2 leads to accelerated atherosclerosis with upregulation of inflammation." (PMID 40825505, 2025). "One potential pathogenetic mechanism underlying this association postulates that JAK2 V617F-positive leukocytes upregulate matrix metalloproteinase-9, which is known to be associated with the development of atherosclerosis." (PMID 39062663, 2024). "Association between JAK2 V617F mutation and atherosclerosis is being more thoroughly investigated in the last decade, however, little is known about correlation between allele burden and CVS risk." (PMID 39361963, 2024). "Previous studies showed, that TET2 or JAK2 clonal mutation increases IL-6 and IL-1β production in myeloid cells supporting accelerated atherosclerosis." (PMID 38138958, 2023). "To determine the essential in vivo role of macrophage (M)-Jak2 in atherosclerosis, we generate atherosclerosis-prone ApoE-null mice deficient in M-Jak2." (PMID 35169231, 2022). "As such, mice deficient in M-Jak2, as well as mice that were treated with JAK2 inhibitor, developed accelerated atherosclerosis." (PMID 35169231, 2022). "In a mouse model of atherosclerosis, mice that received bone marrow transplants from JAK2-mutated mice had accelerated atherosclerosis and larger plaques with increased necrotic cores." (PMID 34988471, 2021). "More importantly, we discovered that OSMR-β deficiency attenuated the development of atherosclerosis and improved plaque stability partially through the inhibition of JAK2/STAT3 signaling." (PMID 28258089, 2017).
atherosclerosis (continued). "Taken together, these data suggest that the loss of OSMR-β attenuates the development of atherosclerosis, at least partly, via inhibiting the JAK2/STAT3 signal transduction pathway in macrophages." (PMID 28258089, 2017). "However, normal macrophage JAK2 is atheroprotective, as its deficiency causes impaired cholesterol efflux and accelerated atherosclerosis." (PMID 41544081, 2026). "Therefore, DNMT3A mutations, similar to TET2 and JAK2, link epigenetic regulation of autophagy to macrophage-driven atherosclerosis." (PMID 40244103, 2025). "Interestingly, our results indicate that deletion of Jak2 in platelets also leads to increased atherosclerosis risk with increased plaque burden in the aorta." (PMID 40825505, 2025). "This section explores the mechanisms by which JAK2 mutations disrupt autophagic regulation in macrophages and how this dysregulation accelerates atherosclerosis, setting the stage for understanding potential therapeutic interventions targeting JAK2 and autophagic pathways in atherosclerosis." (PMID 40244103, 2025). "Furthermore, DNMT3A and JAK2 mutations, now known to promote atherosclerosis and HF, drive the proliferation of bone marrow cells with proinflammatory characteristics." (PMID 38162500, 2023). "Loss of myeloid JAK2 promotes atherosclerosis in an ApoE knockout mouse model." (PMID 35169231, 2022). "Janus kinase 2 (JAK2) is a pivotal molecule in inflammatory and metabolic signaling, and Jak2V617F activating mutation has recently been implicated with enhancing clonal hematopoiesis and atherosclerosis." (PMID 35169231, 2022). "It is also well known that different animal models have different lipid and lipoprotein biology which may account for the differences in atherosclerosis susceptibility in response to JAK2 inhibitor." (PMID 35169231, 2022). "It suggests that ruxolitinib may attenuate atherosclerosis by inhibiting JAK2/STAT3/SOCS3 signaling pathway, while the detailed underlying mechanisms still need further studies." (PMID 32169038, 2020). "In cardiovascular contexts, the effect of Jak2 mutations on atherosclerosis was also examined." (PMID 32825226, 2020). "Mech­anistically, the protective effect of OSMR-β deficiency on atherosclerosis may be partially attributed to the inhibition of the JAK2/STAT3 activation in macrophages, whereas OSM stimulation can activate the signaling pathway." (PMID 28258089, 2017). "Our results indicated that high-fat diet and balloon injury of the aorta could cause the occurrence of atherosclerosis and the atherosclerotic rabbit exhibited elevated JAK2 and STAT3 phosphorylation levels, suggesting that the JAK/STAT3 signaling pathway is activated during atherosclerosis." (PMID 32169038, 2020). "The specific function of Jak2 in different tissues and cell types warranted the investigation of platelet Jak2 on inflammation and atherosclerosis." (PMID 40825505, 2025). "We have previously shown that deficiency of Jak2 in adipocytes led to exacerbated systemic insulin resistance and increased adiposity due to impaired lipid homeostasis; and hepatocyte-specific Jak2 KO mice exhibit fatty liver and exacerbated atherosclerosis." (PMID 40825505, 2025). "STAT3 and JAK2 are also involved in numerous cardiovascular diseases, including diabetic cardiomyopathy, atherosclerosis, pathological myocardial hypertrophy and fibrosis, and lipopolysaccharide-induced myocardial injury." (PMID 40361044, 2025). "Together, our data show direct and indirect effects of platelet Jak2 in mediating systemic inflammatory response that likely led to accelerated atherosclerosis in ApoE−/−P-Jak2 KO mice." (PMID 40825505, 2025). "Interleukin-6 (IL-6), a key pro-inflammatory cytokine elevated in atherosclerosis, activates JAK2 signaling and induces the phosphorylation of Beclin 1 (BECN1), a critical protein involved in the initiation of autophagy." (PMID 40244103, 2025).
atherosclerosis (continued). "Jak2V617F activating mutation, which causes constitutively increased Jak2 signaling, in LDL receptor-null mice led to increased atherosclerosis in the aortic root compared to WT controls." (PMID 40825505, 2025). "Given that Jak2 is a major inflammatory mediator, we investigated the essential endogenous role of platelet Jak2 in ApoE−/− model of atherosclerosis." (PMID 40825505, 2025). "The “Lipid and Atherosclerosis” pathway highlights HSP90AB1, IRAK4, and JAK2, which are associated with lipid metabolism and immune responses." (PMID 40621499, 2025). "ApoE-null mice with platelet-specific Jak2 deletion were used to show that Jak2 in platelets plays a critical role in regulating atherosclerosis." (PMID 40825505, 2025). "The anti-inflammatory effects of the JAK2/STAT3 pathway in the context of atherosclerosis were also reported." (PMID 39936945, 2025). "For instance, ApoE-null mice with myeloid-specific Jak2 deletion develop accelerated atherosclerosis despite being protected against high-fat diet–induced obesity, systemic insulin resistance, and inflammation in liver and visceral adipose tissue." (PMID 40825505, 2025). "Activation of the JAK2/STAT3 pathway is strongly linked to the IL‐6 cytokine family, which plays a critical role in endothelial cell dysfunction associated with atherosclerosis." (PMID 40166646, 2025). "Given the pivotal role of this phenotypic switch in the pathogenesis of atherosclerosis, it is crucial to identify effective therapeutic agents that target the JAK2/STAT3/KLF4 pathway to inhibit the transition of VSMCs to macrophage-like cells." (PMID 39062998, 2024). "Our research illustrates that quercetin inhibits the KLF4-mediated phenotypic switch of VSMCs to macrophage-like cells and reduces atherosclerosis by suppressing the JAK2/STAT3 pathway." (PMID 39062998, 2024). "The connection between CH and atherosclerosis has been primarily identified for somatic mutations in TET 2 (Tet methylcytosine dioxygenase 2) and JAK 2 (Janus kinase 2) genes." (PMID 38892201, 2024). "Fatty acid binding protein 4 upregulates macrophage inflammation-related interleukin-6 (IL-6) level and regulates lipid metabolism in atherosclerosis induced by activation of the JAK2/STAT2 pathway." (PMID 38835896, 2024). "Previous animal models showed that JAK2 inhibitors attenuate atherosclerosis in mice and rabbit models." (PMID 38138958, 2023). "There are plenty of preclinical trials searching for further treatment strategies in atherosclerosis, such as JAK2 inhibitors and chemokine receptor targeting therapies." (PMID 38138958, 2023). "We previously found that PIAS3 was negatively associated with the JAK2/STAT3 activation and inflammatory responses in macrophages during atherosclerosis." (PMID 37008329, 2023). "In the model of atherosclerotic rabbits, the phosphorylation levels of JAK2 and STAT3 were increased, and the expression of SOCS3 was also upregulated, indicating that inhibition of JAK2/STAT3/SOCS3 signaling can alleviate atherosclerosis." (PMID 37089432, 2023). "JAK2/STAT2 pathway contributes to homocysteine-accelerated macrophage inflammation, adding to the risk for atherosclerosis." (PMID 36969251, 2023). "An increasing number of studies have demonstrated that the JAK2/STAT3 signaling pathway is strongly activated when modulating atherosclerosis, including endothelial cell dysfunction, macrophage polarization, inflammation and immunity." (PMID 37237975, 2023). "The JAK2/STAT3 pathway is intimately linked to the IL-6 cytokine family, which plays a critical role in endothelial cell dysfunction during atherosclerosis." (PMID 35607519, 2022). "Using mice with M-Jak2 deletion, and mice treated with ruxolitinib, a clinically available JAK2 inhibitor, we showed that M-Jak2 is essential for attenuation of atherosclerosis." (PMID 35169231, 2022).
atherosclerosis (continued). "To understand the mechanistic role of myeloid Jak2 in atherosclerosis, we treated BMDM with an LXR agonist, TO91317 that increases the transcription of ABCA1 and ABCG139–41." (PMID 35169231, 2022). "Overall, we show in this study using multiple approaches, including specific genetic deletion of Jak2 in myeloid cells that leads to accelerated atherosclerosis that is recapitulated by systemic JAK2 inhibition in vivo." (PMID 35169231, 2022). "Pharmacologic JAK2 inhibition with ruxolitinib also leads to defects in cholesterol efflux and accelerates atherosclerosis." (PMID 35169231, 2022). "With respect to Jak2-mutants, alterations in macrophage function also appear to contribute to atherosclerosis." (PMID 36355225, 2022). "Pharmacologic inhibition of JAK2 in another mouse model of atherosclerosis led to decreased atherosclerotic burden." (PMID 34988471, 2021). "It has reported that the JAK/STAT signaling pathway is important in atherosclerotic lesion development, so we next explored the function of ruxolitinib, an inhibitor of JAK2, in atherosclerosis progress of rabbits." (PMID 32169038, 2020). "In this study, we have assessed the impact of treatment with TG101348 (fedratinib), a selective inhibitor of JAK2, on myelopoiesis and atherosclerosis in WD-fed Apoe−/− mice." (PMID 32086626, 2020). "Our studies demonstrate for the first time that selective inhibition of JAK2 reverses excessive myelopoiesis and reduces atherosclerosis in hypercholesterolemic mice." (PMID 32086626, 2020). "In this study, we designed experiments to further investigate the effect of JAK2/STAT3/SOCS3 signaling in rabbit atherosclerosis process." (PMID 32169038, 2020). "Mechanistically, the role of OSMR-β in the development of atherosclerosis is partially mediated through regulation of the JAK2/STAT3 signaling pathway." (PMID 28258089, 2017). "Other up-regulated genes that are also targets of miR-193 included mediators of obesity, related inflammatory cytokine and leptin signaling (JAK2) as well as atherosclerosis (SCARF2/SREC-I)." (PMID 26258540, 2015). "On the other hand, macrophage-specific Jak2 KO mice are protected against high-fat diet–induced systemic insulin resistance, obesity, and inflammation, but paradoxically also show increased atherosclerosis in an ApoE-null model." (PMID 40825505, 2025). "In this study, we investigated the in vivo role of platelet Jak2 in atherosclerosis." (PMID 40825505, 2025). "This suggests that JAK2 could be a potential therapeutic target to modulate macrophage autophagy and inflammation in atherosclerosis." (PMID 40244103, 2025). "Additionally, JAK2 mutations, specifically JAK2V617F, have been shown to promote thrombosis and atherosclerosis in mouse models." (PMID 39997650, 2025). "Similar to the complement cascade, the JAK2/STAT3 pathway could be a double-edged sword in atherosclerosis." (PMID 39936945, 2025). "It was hypothesized that the dual role of the JAK2/STAT3 pathway in atherosclerosis depends on which isoform of STAT3 is activated: the pro-inflammatory STAT3α or the anti-inflammatory STAT3β." (PMID 39936945, 2025). "While platelets’ role in hemostasis and thrombosis is well-established in CVD, the essential role of platelet Jak2 in mediating inflammation in atherosclerosis is unknown." (PMID 40825505, 2025). "Interestingly, the deletion of Jak2 in various cell types also paradoxically leads to increased atherosclerosis." (PMID 40825505, 2025). "Furthermore, hepatic Jak2 deletion in male ApoE or LDL receptor-null mice also led to accelerated atherosclerosis." (PMID 40825505, 2025). "Like ASXL1, JAK2 VF CHIP also drives atherosclerosis by activating the AIM2 inflammasome." (PMID 39352379, 2024).
atherosclerosis (continued). "JAK2 V617F somatic variants exhibited a negative effect size for abdominal aortic aneurysms (effect size = −0.026) and atherosclerosis of the aorta (effect size = −0.034, although not statistically significant)." (PMID 39062663, 2024). "Among them, CD36, CDC42, JAK2, and STAT3 proteins were closely associated with atherosclerosis and foam cells, and their protein expressions were opposite to those of the ox-LDL group and converged with those of the control group after the sinapine base intervention." (PMID 36903257, 2023). "Although AIM2 inflammasome activation has been shown to be sufficient to promote atherosclerosis in Jak2 CH, our findings suggest that other pathways may also contribute to ASXL1-mediated CVD risk." (PMID 37498674, 2023). "Second, it was dependent on the identity of the affected gene with mutations in JAK2 leading to a 12-fold increase, whereas mutations in the most frequently affected genes TET2 and DNMT3A conferred a two-fold increase in the risk of developing atherosclerosis." (PMID 36355225, 2022). "We therefore assessed whether myeloid Jak2 deletion may affect clonal hematopoiesis which may have contributed to the accelerated atherosclerosis seen in M-Jak2 KO mice." (PMID 35169231, 2022). "In this study, we examined the specific role of macrophage Jak2 in atherosclerosis." (PMID 35169231, 2022). "Therefore, the aim of the present work was to investigate the effect of FABP4 on regulating the JAK2/STAT2 pathway in macrophage inflammation in atherosclerosis." (PMID 34725437, 2022). "Moreover, they were all positively associated with RBP4, indicating that RBP4 participates in the formation of atherosclerosis by the JAK2/STAT3 signaling pathway." (PMID 35082965, 2022). "To explore the mechanism by which 3C prevents atherosclerosis development, we hypothesized that 3C might suppress JAK2/STAT1 signaling through activating AMPK." (PMID 33901014, 2021). "Taken together, the inhibition of JAK2/STAT3/SOCS3 signaling pathway may be a novel method for the clinical treatment of artery atherosclerosis." (PMID 32169038, 2020). "Hyperlipidemia, one of the most important risk factors account for the further development of atherosclerosis, can activate the JAK/STAT signaling of vascular endothelial cells through phosphorylation of JAK2 and subsequently STAT3, leading to the deterioration of atherosclerosis." (PMID 32169038, 2020). "Taken together, our findings suggest that the inhibition of JAK2/STAT3/SOCS3 signaling may attenuate atherosclerosis in rabbits." (PMID 32169038, 2020). "From those results, we finally concluded that the inhibition of JAK2/STAT3/SOCS3 signaling may attenuate atherosclerosis in rabbits." (PMID 32169038, 2020). "Notably, activation of the JAK2/STAT3 pathway is closely associated with the IL-6 cytokine family, which plays an essential role in endothelial cell dysfunction during atherosclerosis." (PMID 31588227, 2019). "Therefore, it could be hypothesized that AATP exerts anti-inflammatory effects on atherosclerosis by inhibiting the JAK2/STAT3 signaling pathway." (PMID 40647133, 2025). "However, the role of platelet Jak2 in regulating platelet-mediated inflammatory response involved in atherosclerosis remains unclear." (PMID 40825505, 2025). "The motivation to inhibit JAK2 signaling to limit atherosclerosis stems from studies showing that constitutively activating JAK2 mutants lead to biased myelopoiesis, which links to the development of ASCVD." (PMID 39352379, 2024). "However, the essential in vivo role of myeloid Jak2 (M-Jak2) and the specific mechanisms through which it can regulate atherosclerosis is unknown." (PMID 35169231, 2022). "JAK2 is a non-receptor tyrosine kinase associated with several cytokine receptors and is critically involved in different processes such as erythropoiesis, atherosclerosis, endothelial cell activation, and myocardium inflammation." (PMID 32748835, 2020).